AR (androgen receptor)
Diseases named in the same sentence as AR in open-access papers (continued):
Sharing a sentence is not in itself a finding about the gene and the disease.
prostate carcinoma (continued). "Prostate cancer is primarily characterized by a dependence on the axis of androgen and its cognitive receptor, the nuclear receptor (NR) androgen receptor (AR), which plays roles in carcinogenesis, cancer development, disease progression, and treatment resistance." (PMID 31212954, 2019). "Therefore, AR axis-targeting therapeutics such as androgen-deprivation therapy and antiandrogens have been the gold-standard treatments for recurrent or advanced prostate cancer." (PMID 31212954, 2019). "It was shown that SNCG interacts with AR and promotes prostate cancer cellular growth and proliferation by activating AR transcription in an androgen-dependent manner, whereas SNCG was almost undetectable in benign or androgen-independent tissues prostate lesions." (PMID 31238876, 2019). "The inhibition of BRD4, a member of the Bromodomain and ExtraTerminal (BET) family of bromodomain-containing proteins, was recently shown to reduce levels of Androgen Receptor (AR) driven target genes in prostate cancer, and reduce tumor burden in murine models." (PMID 31653272, 2019). "Increases androgen receptor degradation in androgen-dependent prostate cancer cells." (PMID 31801262, 2019). "AR was demonstrated to protect prostate cancer cells from DNA damage in vitro." (PMID 31151151, 2019). "Considering the effect of kaempferol on the cell growth of AR-positive prostate cancer cells significantly compared with that of AR-negative ones or nonmalignant prostate cells, we further evaluated the effect of kaempferol on apoptosis of prostate cancer cells." (PMID 31871879, 2019). "In this regard, we have discovered a role of AR in prostate cancer cell telomere stability." (PMID 31083651, 2019). "In addition, metastases derived from castration-resistant prostate cancers, besides showing AR amplification, display also frequent somatic deletions of the BRCA2 gene." (PMID 31284411, 2019). "Interestingly, a recent study showed that EZH2 inhibitors upregulated androgen receptor expression and sensitized the prostate cancers to anti-androgen therapy." (PMID 31704972, 2019). "Recently, some studies have reported suppressive effects of androgen/AR signaling in prostate cancer cells, therefore suppression of AR function itself may cause CRPC." (PMID 30871130, 2019). "The approval of upfront abiraterone for castration-sensitive prostate cancer and the approval of enzalutamide and apalutamide for non-metastatic castration resistant prostate cancer have led to early utilization of potent AR signaling inhibitors in treating advanced prostate cancer." (PMID 31404966, 2019). "Importantly, our study demonstrates that the GATA2 inhibitor K7174 perturbs enzalutamide-liganded AR-mediated transcription activation and markedly enhances the ability of enzalutamide to decrease prostate cancer cell proliferation." (PMID 31501863, 2019). "Given the prevalence of aberrant androgen signaling pathways in prostate cancer initiation and progression, we then generated R26hARL/wt:p16L/L: PB-Cre4 compound mice, in which conditional expression of the human AR transgene and deletion of p16Ink4a co-occur in prostatic luminal epithelial cells." (PMID 30677079, 2019). "Prostate cancer is characterized by the dysregulation of several intracellular pathways and its onset and progression are determined by the presence and activation status of the androgen receptor (AR), which plays a key role during all phases of tumor growth." (PMID 31013746, 2019). "In prostate cancer, BMP signalling has been implicated in the androgen-independent AR signalling associated with castration resistance, though its mode of action remains unclear." (PMID 31589603, 2019). "Therapeutic targeting of AR in prostate cancer using antiandrogens may be considerably enhanced by targeting of Stat5, through a stimulation of proteosomal degradation of AR liganded by antiandrogens." (PMID 31366128, 2019).
prostate carcinoma (continued). "The activation of the androgen receptor (AR) with a synthetic androgenic agonist (R1881) in the human androgen-dependent prostate cancer cells LNCaP and LAPC4 promotes an increase in mRNA levels of Krebs cycle enzymes (FH, 2OGDH), ATPS, and ND1, as well as OxPhos flux." (PMID 31600993, 2019). "Because FKBP51 is overexpressed in cancer cells, the oncogene activity of AR is enhanced and the tumour suppressor action of GR results inhibited, which contributes to the bad prognosis related to the expression of this immunophilin in prostate cancer." (PMID 30717249, 2019). "The androgen receptor is one of the key targets for prostate cancer treatment." (PMID 31581661, 2019). "However, a putative CRM1 binding site was identified near the C-terminus of the AR, and the rapid nuclear export of AR that occurs upon inhibition of GSK-3β in prostate cancer cells is blocked by Leptomycin B29,30." (PMID 30644418, 2019). "Indeed, androgen ablation by an inhibitor of androgen biosynthesis, abiraterone acetate, and by enzalutamide, an AR antagonist that prevents nuclear translocation and chromatin binding, extend survival of prostate cancer patients." (PMID 30871232, 2019). "Instead, olaparib decreased AR levels only in BRCA2-knockdown prostate cancer cells." (PMID 31284411, 2019). "Androgen receptor (AR) inhibitors represent the mainstay of prostate cancer treatment." (PMID 31855178, 2019). "EPI-506 is an antagonist of the transcriptional regulatory region AF-1 (activation function-1) of the AR, a region present in the NTD of the receptor, and acts as an inhibitor of the growth of prostate cancer cells with aberrant AR activity, including cells with constitutively active AR-7." (PMID 31366128, 2019). "In this study, no AR aberration was observed in the neoadjuvant setting, probably because AR amplification and mutations are typically later events in the process of prostate cancer progression (present in 60% of metastatic disease)." (PMID 31689899, 2019). "Furthermore, simultaneously inhibiting both the AR and PI3K/AKT pathways caused dramatic reductions in tumor volume in prostate cancer models, including PTEN-deficient mice and human xenografts." (PMID 34926721, 2019). "In prostate cancer, a recent study revealed that σ1R expression contributes to cell resistance to ER stress, and to the development of treatment-induced castration-resistant prostate cancer by promoting androgen receptor resurgence." (PMID 31780884, 2019). "CAMKK2 is induced in prostate cancer cells by AR signaling and CAMKK2 in turn activates AMPK." (PMID 31366128, 2019). "Characterization of prostate cancer cells with low vs. high AR output." (PMID 30644358, 2019). "We found that it could suppress the activity of both AR‐FL and AR‐Vs to inhibit the growth of prostate cancer cells at an in vivo achievable concentration." (PMID 30905075, 2019). "In addition, PIK3CA, AKT1, and MAPK1 directly interacted with AR, which was a naringenin-mediated protein gene as well and participated in prostate cancer pathway." (PMID 30918758, 2019). "In addition to this genomic heterogeneity, primary prostate cancers also display heterogeneity in AR transcriptional output, measured by an AR activity score." (PMID 30644358, 2019). "A better understanding of how GREB1 and androgen receptor cooperate may also be useful for developing new drugs to treat prostate cancer." (PMID 30644358, 2019). "Finally, in prostate cancer, androgen receptor (AR) activity is important for initiation and progression." (PMID 31003534, 2019). "However, it has been reported that most initial responders to AR inhibitors alone in prostate cancer patients eventually develop acquired resistance." (PMID 30987323, 2019). "Clinical resistance arises from AR overexpression or ligand-independent constitutive activation, suggesting that complete AR elimination could be a novel therapeutic strategy in prostate cancers." (PMID 31431473, 2019).
prostate carcinoma (continued). "AR is already a therapeutic target, and the availability of selective AR inhibitors (e.g., bicalutamide, enzalutamide, apalutamide) approved for the treatment of prostate cancer has opened up the possibility of their use in BC patients whose tumors express AR." (PMID 31110518, 2019). "Hence, the identification of mechanisms and chemical agents that prevent AR signaling warrant thorough investigation for the improvement of new prostate cancer drugs." (PMID 31801262, 2019). "The role FOXC1 plays in prostate cancer progression is unknown, but FOXC1 expression may be linked to androgen receptor levels." (PMID 31478829, 2019). "However, several reports have emphasized the importance of AR splicing in prostate cancer progression." (PMID 30939845, 2019). "While HOXB13 regulates Androgen Receptor (AR) functions in a context dependent manner, its critical effectors in prostate cancer (PC) metastasis remain largely unknown." (PMID 31273254, 2019). "It has been described that FNDC1 regulates the androgen receptor in prostate cancer." (PMID 31093274, 2019). "Clinical observation on patients with prostate cancer showed a positive correlation between AR and β-catenin expression in the tumorigenic cells, and an activated Wnt/β-catenin pathway and AR expression in prostate cancer strongly correlated with the metastasis and aggressiveness of the tumors." (PMID 31100850, 2019). "The central role of androgens and the AR in prostate cancer, and the poor clinical outlook of castration-resistance prostate cancer (CRPCa), have made it crucially important to identify androgen-regulated target genes and mechanisms of function –particularly those that relate to metastasis." (PMID 31478829, 2019). "Ganetespib, an HSP90 inhibitor, targets several oncogenic proteins in prostate cancer cells, including AR and PI3K/AKT pathway; this drug, combined with castration, induced more pronounced tumor regressions and delayed castration resistance relative to either monotherapy." (PMID 31366128, 2019). "Therefore, I have summarized these representative reports showing several new driving forces for prostate cancer progression and enhanced AR signaling." (PMID 30939845, 2019). "In prostate cancer, plasma AR status, given its role in patients treated with different drugs, could become an important predictive biomarker to guide treatment selection in mCRPC, along with other factors such as PSA level." (PMID 31689899, 2019). "However, the analysis of the AR pathway, including several known activators, coactivators, and corepressors, showed alterations in 56% of primary prostate cancers and 100% of metastases." (PMID 31366128, 2019). "The gastrointestinal gene signature was orchestrated by the transcription factors HNFG4 and HNF1A; the induction of HNFG4 and HNF1A-mediated pathway is required to sustain the proliferation of SPINK1-overexpressing prostate cancer cells, independently of AR signaling." (PMID 31366128, 2019). "Given the important role that AR plays in prostate cancer, such epigenetic regulation of its activity and the effect on down-stream signaling by resveratrol is an encouraging finding that gives hope for its possible use as a therapy against prostate cancer." (PMID 30781847, 2019). "TGF-β and AR synergistically stimulate apoptosis in prostate cancer cells overexpressing TGFBR2." (PMID 31842336, 2019). "First, human prostate cancer cells were separated according to their androgen receptor output." (PMID 30644358, 2019). "Therapies aimed at inducing the degradation of AR may, thus, offer an effective way to curb prostate cancer development and progression." (PMID 31431473, 2019).
prostate carcinoma (continued). "It has been determined that AR plays an important role in prostate cancer bone metastasis." (PMID 31753020, 2019). "Currently, several BET protein inhibitors (e.g., ZEN003694, OTX015/MK-8628, ABBV-075, INCB057643, GSK525762/I-BET762, GS-5829) are in phase I/II clinical trials, with some studies specifically assessing their efficacy in prostate cancer patients alone or in combination with AR-targeted therapies." (PMID 31143708, 2019). "Since ESRP2 expression was repressed by ADT in patient prostate cancer tissue, we next investigated whether AR inactivation may influence mRNA splice isoforms that correlate with cancer progression." (PMID 31478829, 2019). "However, ENZ-mediated radiosensitization was observed in low AR-expressing prostate cancer cell line DU145." (PMID 30933998, 2019). "Interestingly, EZH2 serves as a coactivator of AR through direct interaction to facilitate its oncogenic function in cells of castration-resistant prostate cancer." (PMID 31481081, 2019). "FoxA1 also has androgen receptor-independent function in prostate cancer." (PMID 31552182, 2019). "Stromal AR has also been shown to mediate prostate cancer metastasis." (PMID 31013716, 2019). "We thought that IL-7Rα expression may be a characteristic of advanced prostate cancer (i. e., AR-independence)." (PMID 31061414, 2019). "This review will focus on AR testing in plasma that may have clinical utility for treatment selection in advanced prostate cancer." (PMID 31689899, 2019). "Aberrant activation of the androgen receptor (AR) may play a critical role in castration resistant prostate cancer." (PMID 31819114, 2019). "CDK9-mediated phosphorylation can reactivate AR signaling in castration-resistant prostate cancer." (PMID 30841549, 2019). "Thus, the study of genetic models of prostate cancer showed an essential role for PARP-1 in sustaining AR transcriptional function; furthermore, PARP-1 activity increases during disease progression." (PMID 31366128, 2019). "Functionally, DAX1 repressed AR activity in androgen-dependent LNCaP prostate cancer cells." (PMID 31212954, 2019). "AR null prostate cancer xenografts were also shown to be sensitive to inhibitors of MAPK or FGFR." (PMID 30804427, 2019). "TGF-β signaling in prostate cancer interplays with the activity of the androgen receptor (AR)." (PMID 31842336, 2019). "Resveratrol inhibits the AR signaling pathway in prostate cancer by affecting PCGEM1 and PRNCR1." (PMID 31208095, 2019). "The reason why a higher TST level was associated with a favorable response to Enza and Abi may be related to the AR dependency of prostate cancer." (PMID 30978937, 2019). "AR-mediated DSBs in prostate cancer may provide clues to the recurrent ESR1 breakpoints for ESR1 fusions seen in breast cancer." (PMID 31106278, 2019). "Having confirmed castration levels of testosterone in the APSCE to be comparable with the conventional model of ADT in steroid-depleted medium (SDM), we noted a paradoxical upregulation of AR target gene expression following culture of castration-resistant prostate cancer cells CWR22Rv1 in APSCE." (PMID 30742096, 2019). "The main downstream effector of ACK1 is AR, and both breast and prostate cancers are hormone-regulated cancers, indicating the potential of ER as another hormone receptor that interacts with ACK1, possibly making breast cancer cells more sensitive to radiotherapy by inhibiting ACK1-ER signaling." (PMID 31772931, 2019). "In addition, we identified that treatment with Roscovitine, as a pan-CDK inhibitor, decreased the nuclear localization of AR protein in prostate cancer cells, while the cytosolic accumulation of AR protein is increased in prostate cancer cells." (PMID 31395805, 2019). "Recent studies have stressed the relevance of AR heterogeneity in prostate cancer tissue." (PMID 31366128, 2019). "Kaempferol could promote apoptosis of LNCaP cells, AR-positive prostate cancer cells, in a dose-dependent manner significantly." (PMID 31871879, 2019).
prostate carcinoma (continued). "Interestingly, treatments of prostate cancer cells with FK506 relates to the inhibition of the androgen-dependent response mediated by the AR." (PMID 30717249, 2019). "In advanced prostate cancer (PCa), the dependency of tumor cells on androgen receptor (AR) signaling has made targeting this pathway a primary focus of drug development, with patients receiving androgen deprivation therapy (ADT) as first line treatment for recurrent disease." (PMID 31379747, 2019). "Given the significance of both AR and p16Ink4a alterations in human prostate cancers, we developed R26hARL/wt:p16L/L:PB-Cre4 compound mice in which the deletion of the p16Ink4a gene and conditional expression of the human AR transgene co-occur in the prostatic luminal epithelium." (PMID 30677079, 2019). "It has been suggested that the activation of AR in hypoxic conditions is HIF-1α mediated, hence targeting HIF-1α could influence the AR stimulatory effect of hypoxia in castration-resistant prostate cancer." (PMID 31151317, 2019). "This raises the hypothesis that the androgen signal can suppress the expression of IL-7Rα in AR-positive prostate cancer cells because IL-7Rα is expressed only in AR-negative prostate cancer cells." (PMID 31061414, 2019). "Common genetic alterations in prostate cancer include HPCI mutation, losses or down-regulation of the tumor suppressor protein NKX3.1, loss or mutation of PTEN, TMPRSS2-AR or ERG1-AR gene fusion, and AR upregulation." (PMID 31088536, 2019). "The protective role of sulforaphane and capsaicin on prostate cancer may rely on mechanisms involving the inhibition of Tip60, AR and HIF-1α effects." (PMID 31671779, 2019). "The prosurvival protein kinase CK2, androgen receptor (AR), and nuclear factor kappa B (NFκB) interact in the function of prostate cells, and there is evidence of crosstalk between these signals in the pathobiology of prostate cancer (PCa)." (PMID 31197122, 2019). "Androgen/AR targeted therapies (ATTs) exploit this dependence in advanced prostate cancer (PCa) patients, and may involve parallel or sequential use of differential androgen synthesis or AR inhibitors." (PMID 30194451, 2019). "A study on the clinical relevance of miR-34b-3p, although in relation to prostate cancer, revealed that miR-34b-3p could control transcription of the androgen receptor (AR) in vitro." (PMID 31737638, 2019). "In addition, BRD4 interacts with the N-terminal domain of AR and induces AR-mediated gene transcription and BET inhibitor, JQ1 effectively disrupts the interaction between BRD4 and AR leading to cytotoxic efficacies in advanced prostate cancer model." (PMID 31527644, 2019). "Interestingly, it has been shown quite convincingly in prostate cancer models that AR and PI3K signaling inhibit each other in a reciprocal fashion, and when one pathway is inhibited, the other becomes more active." (PMID 34926721, 2019). "It is thus likely that ZFHX3 is also a regulator of androgen/AR signaling in prostate cancer." (PMID 30979864, 2019). "Based on the multiple roles of AR in prostate cancer, CDK5 might be one of the relevant regulators in the cancer progression; this is discussed in the following section." (PMID 31395805, 2019). "Taken together, these studies support the hypothesis that polyphenols are able to modulate AR and its transactivation pathways in prostate cancer models, both in cell culture and in animal experiments." (PMID 30823649, 2019). "Thus, loss of ERF activity by rare genomic loss-of-function mutations or by competition with the TMPRSS2-ERG oncogenic product leads to activation of the androgen receptor pathway and prostate cancer." (PMID 31366128, 2019). "Human prostate adenocarcinoma cells lymph node carcinoma of the prostate (LNCaP) with high expression of AR has long been considered as the closest model for prostate cancer study, and its proliferation depends on the activation of androgen receptor signaling pathway." (PMID 31827406, 2019).